ANTXR1 (ANTXR cell adhesion molecule 1)
Diseases named in the same sentence as ANTXR1 in open-access papers (continued):
Sharing a sentence is not in itself a finding about the gene and the disease.
ischemia (2 papers, 2016 to 2025). A hypoperfusion of the BLOOD through an organ or tissue caused by a PATHOLOGIC CONSTRICTION or obstruction of its BLOOD VESSELS, or an absence of BLOOD CIRCULATION. "By facilitating collagen turnover in response to stress, our data implicate ANTXR1 as a pathogenic driver of heart disease induced by ischemia, hypertension and obesity." (PMID 41039173, 2025). "Together with elevated expression in HCM/DCM, these findings suggest that ANTXR1 expression mirror fibrosis driven by both ischemia and hypertension." (PMID 41039173, 2025).
metastatic melanoma (2 papers, 2023 to 2024). A melanoma that has spread from its primary site to another anatomic site. "Indeed, a Phase 2 study (NCT019733322) involving vaccination with autologous dendritic cells combined with immunomodulated radiotherapy and/or preleukapheresis interferon-alfa in metastatic melanoma is being conducted to explore TEM8/ANTXR1 upregulation." (PMID 37998358, 2023).
small cell lung carcinoma (2 papers, 2021 to 2024). Small cell lung cancer (SCLC) is a highly aggressive malignant neoplasm, accounting for 10-15% of lung cancer cases, characterized byrapid growth, and early metastasis. "Despite the absence of any interactions between ANTXR1 glycans and SVV capsid, ANTXR1 deglycosylation was able to abrogate viral entry into the small-cell lung cancer cell line H446wt, highlighting its stringent effect on receptor function." (PMID 33924774, 2021).
viral infection (2 papers, 2022 to 2025). "The CD163, ANPEP, DNAJC14, and ANTXR1 knockout pigs proved resistant to viral infections." (PMID 41465565, 2025).
acute myocardial infarction (1 paper, 2025). Necrosis of the myocardium, as a result of interruption of the blood supply to the area. "Genetic disruption of Antxr1 and treatment with human neutralizing antibodies prevented heart deterioration following acute myocardial infarction." (PMID 41039173, 2025).
adenoma (1 paper, 2021). A neoplasm arising from the epithelium. "These authors found that OPLAH alone and/or a combination of a few methylated DNA markers (ARHGEF4, LRRC4, ANTXR1, PITX1) can discriminate adenomas and CRC in LS patients." (PMID 34201893, 2021).
adenovirus infection (1 paper, 2020). "Antxr1 expression was upregulated 3.7 times by Runx2-expressing adenovirus infection in the microarray analysis." (PMID 32244499, 2020).
bladder cancer (1 paper, 2024). "Our findings confirm the unique role of high ANTXR1 expression in bladder cancer as a precursor for key signaling pathways that induce tumor aggressiveness, metastasis and invasion, indicating a poor prognosis." (PMID 39917181, 2024). "Of more than 25 membrane proteins, only CXCR7, SPON2 and ANTXR1 had a significant difference in probability of survival in bladder cancer patients (only ∼10%)." (PMID 39917181, 2024). "The role of ANTXR1 as a prognostic biomarker has been demonstrated not only in this study for bladder cancer, but for other types of cancer." (PMID 39917181, 2024). "Here, we studied the effect of ANTXR1 gene expression in different types of cancers and chose bladder cancer to understand the implications of high expression of ANTXR1 as a poor prognostic marker." (PMID 39917181, 2024). "Here, we demonstrate that elevated expression of ANTXR1 in bladder cancer showed a statistical difference not only in overall survival (OS) but in progression-free survival (PFS), confirming the prognostic biomarker power of ANTXR1 expression." (PMID 39917181, 2024). "To further investigate the relationship between different types of survival, more specifically PFS and DFS, and expression of ANTXR1 in bladder cancer patients, we analyzed the probability of survival for bladder cancer patients according to these parameters." (PMID 39917181, 2024). "For bladder cancer, the impact of ANTXR1 expression showed a statistical difference not only in OS but in PFS, confirming the prognostic biomarker power of ANTXR1 expression." (PMID 39917181, 2024). "In conclusion, in this paper we demonstrated that ANTXR1 expression has a unique role as a prognostic biomarker not only for bladder cancer, but also for other types of cancer." (PMID 39917181, 2024).
bladder urothelial cancer (1 paper, 2024). "Only two (bladder urothelial cancer and colorectal adenocarcinoma) out of the eleven types of cancer analyzed showed a statistically significant difference of the immune score with different levels of expression of ANTXR1." (PMID 39917181, 2024).
cataract (1 paper, 2022). Partial or complete opacity of the crystalline lens of one or both eyes that decreases visual acuity and eventually results in blindness. "A mechanistic link between cataracts and ANTXR1 is not known." (PMID 35322150, 2022).
endothelial dysfunction (1 paper, 2022). In vascular diseases, endothelial dysfunction is a systemic pathological state of the endothelium (the inner lining of blood vessels) and can be broadly defined as an imbalance between vasodilating and vasoconstricting substances produced by (or acting on) the endothelium. "As OSA has been found to be associated with the endothelial dysfunction, our findings may suggest that the downregulated expression of ANTXR1 could be associated with the endothelial dysfunction of OSA patients." (PMID 35480887, 2022).
epilepsy (1 paper, 2014). A brain disorder characterized by episodes of abnormally increased neuronal discharge resulting in transient episodes of sensory or motor neurological dysfunction, or psychic dysfunction. "In conclusion, miR-487a may be the first identified element of a miRNA signature that may be useful for a prognostic evaluation of post-surgical epilepsy and form the basis for mechanistic studies that may lead to the identification of new therapeutic targets, like ANTXR1." (PMID 25148080, 2014).
esophageal tumor (1 paper, 2022). "In addition, ANTXR1 inhibition has been reported to reduce esophageal tumor cell proliferation, block the G0/G1 phase, and promote cell apoptosis." (PMID 36065334, 2022).
head and neck cancer (1 paper, 2022). A primary or metastatic malignant neoplasm affecting the head and neck. "ANTXR1 has been previously associated with metastasis in head and neck cancer patients with nasopharyngeal tumors and other oral disorders." (PMID 35459784, 2022).
heart failure (1 paper, 2025). Inability of the heart to pump blood at an adequate rate to meet tissue metabolic requirements. "Thus, ANTXR1-mediated collagen turnover during heart failure is both maladaptive and druggable, providing avenues for therapeutic intervention." (PMID 41039173, 2025). "Here we show that ANTXR1/TEM8, a pathology-induced transmembrane protein required for collagen removal, exacerbates injury in multiple models of heart failure." (PMID 41039173, 2025).
Hypertension (1 paper, 2025). The presence of chronic increased pressure in the systemic arterial system. "Collectively, these results show that ANTXR1 inhibition improves cardiac function across diverse models of MI, hypertension and HFpEF." (PMID 41039173, 2025). "Given the central role of TGFβ in CF activation, myofibroblast differentiation and fibrosis, and its modulation by T8Ab in both MI and hypertension models we next investigated the impact of ANTXR1 on TGFβ signaling." (PMID 41039173, 2025). "Co-IF revealed strong ANTXR1 and THBS4 colocalization within the expanding CF population following hypertension, recapitulating the pattern observed post-MI." (PMID 41039173, 2025).
inflammatory breast carcinoma (1 paper, 2011). An advanced, invasive breast adenocarcinoma characterized by the presence of distinct changes in the overlying skin. "Interestingly, both Antxr1 and Ahrgap18 are over-expressed in human lobular and inflammatory breast cancer." (PMID 22087314, 2011).
ischemic heart disease (1 paper, 2025). "To assess ANTXR1 in ischemic heart disease, we first examined protein expression in hearts from post-MI transplant recipients." (PMID 41039173, 2025).
neuroendocrine carcinoma (1 paper, 2022). A malignant neuroendocrine neoplasm composed of cells containing secretory granules that stain positive for NSE and chromogranin. "The tropism of SVV-001 for neuroendocrine cancer, mediated by upregulated TEM8/ANTXR1 can inform this paradigm and opens the door for novel uses of SVV-001 to target these tumor types." (PMID 36090051, 2022). "Although this association was identified in SCLC, it is likely, given TEM8/ANTXR1 is the receptor for SVV-001, that SVV-001 permissive subtypes of other neuroendocrine cancers share similar features to SCLC-N, including elevated TEM8/ANTXR1 and low expression of IFN genes." (PMID 36090051, 2022).
neuroendocrine tumors (1 paper, 2022). "It is clear that well differentiated neuroendocrine tumors express high levels of SSTR2, but a connection between SSTR2 and pathologic angiogenesis, possibly associated with TEM8/ANTXR1 is only speculation at present." (PMID 36090051, 2022). "Although there is no published data about TEM8/ANTXR1 upregulation in well differentiated neuroendocrine tumors, given the permissivity towards SVV-001, it is likely that upregulated TEM8/ANTXR1 is present in a subset of these tumors." (PMID 36090051, 2022). "However, understanding SVV-001 and the unique tumor microenvironment, represented by upregulation of TEM8/ANTXR1, that it targets, has the potential to provide additional clues about mechanisms of resistance to immunotherapy and chemotherapy in neuroendocrine neoplasms and other cancers." (PMID 36090051, 2022).
Obesity (1 paper, 2025). Accumulation of substantial excess body fat. "ANTXR1 pharmacological blockade also improved heart function in models of pressure overload and obesity-induced heart disease with preserved ejection fraction." (PMID 41039173, 2025).
Oligodontia (1 paper, 2018). The absence of six or more teeth from the normal series by a failure to develop. "A homozygous missense variant c.1312C > T (p.Arg438Cys) in ANTXR1 (anthrax toxin receptor 1) was identified in association with TA (oligodontia) in a Turkish family." (PMID 29772684, 2018).
pancreatic adenocarcinoma (1 paper, 2024). "Comprehensive analysis, together with the pancreatic adenocarcinoma (PAAD) dataset from The Cancer Genome Atlas (TCGA), revealed that the ANTXR1, CMTM6, ITGB6, PIGR, and PTGS2 genes were significantly upregulated in GEM‐resistant PDAC cell lines." (PMID 39488785, 2024).
peripheral arterial disease (1 paper, 2016). A disorder of the arteries supplying the upper and lower extremity and the visceral organs. "Finally, our observation that altered levels of Antxr1 are associated with peripheral artery disease in humans may open the door to development of tests to identify individuals at risk for progressive disease and in greater need of medical intervention." (PMID 26785120, 2016). "Furthermore, Antxr1 expression was elevated in human peripheral artery disease requiring lower extremity bypass surgery." (PMID 26785120, 2016). "To determine whether Antxr1 may contribute to the pathogenesis of human disease, we evaluated Antxr1 expression levels in muscle tissues from patients diagnosed with peripheral artery disease." (PMID 26785120, 2016).
renal fibrosis (1 paper, 2026). A final common manifestation of a wide variety of chronic kidney diseases characterized by glomerulosclerosis and tubulointerstitial fibrosis. "In the context of renal fibrosis phenotype ontology (RENAL_FIBROSIS), upregulation was observed in ANTXR1, MUC1, SLC37A4, and NPHP4, while ARL3 and NPHP3 were significantly downregulated." (PMID 41573374, 2026).
xerostomia (1 paper, 2022). Dryness of the mouth resulting from reduced salivary secretion. "The top test-wise significant finding of this study was that OPC survivors with at least one allelic variant A in SNP rs6546481 or at least one variant allele G in SNP rs4854546 mapped to the ANTXR1 gene had an increased risk of reporting moderate to severe xerostomia." (PMID 35459784, 2022). "The most prominent findings in our study included potential associations of ANTXR1, RTP1, GLT1D1, NLRP9, and EGFLAM genes with xerostomia." (PMID 35459784, 2022). "Therefore, ANTXR1 may also have a critical role in risk of developing xerostomia." (PMID 35459784, 2022).
tumor (117 papers, 2004 to 2025). "Here the authors investigate the impact of chemotherapy on CAF subsets in patients with high-grade serous ovarian cancer, suggesting that residual ANTXR1+ myofibroblasts are associated with inhibition of anti-tumor immunity." (PMID 38346978, 2024). "ANTXR1 expression is generally associated with tumor metastasis, aggressiveness and tumor invasion in different types of tumors." (PMID 39917181, 2024). "While ANTXR1 expression is generally low in adult tissues, it is believed to be upregulated in tumor-associated fibroblasts, endothelium, and pericytes." (PMID 38653789, 2024). "Further analysis using RNAhybrid revealed a high degree of complementarity between tRFGlnCTG and the 3′UTR of Antxr1, a tumour endothelial marker strongly associated with angiogenesis." (PMID 37833999, 2023). "The interplay between cancer stem cells, TEM8/ANTXR1, angiogenesis, and tumor associated macrophages is a potentially important area for further studies." (PMID 36090051, 2022). "Using genetically engineered mouse models, we discovered that solid tumor growth depends upon collagen binding and uptake mediated by the TEM8/ANTXR1 cell surface protein in tumor-associated stroma." (PMID 36400786, 2022). "A concurrent 825 tumor-related gene panel for thoracolumbar metastases revealed several other likely pathogenic variants (ANTXR1 and below), among which DNMT3A is predicted to be an epigenetic driver of high malignancy and dismal prognosis." (PMID 34796114, 2021). "We further assessed the differential landscape of somatic tumor mutation burden (TMB) between the two groups (high vs. low ANTXR1 expression)." (PMID 33385012, 2020). "Consistent with our results, ANTXR1 is widely expressed on tumor-associated perivascular stromal cells, which strongly promotes angiogenesis within the TME." (PMID 32695142, 2020). "ANTXR1 is a tumor-specific endothelial marker implicated in colorectal cancer, and upregulated in tumor angiogenesis." (PMID 29772684, 2018). "Recently, human anthrax toxin receptor 1 (ANTXR1) has been identified as a cellular receptor for SVV in human tumor cells using genome-wide loss-of-function screening." (PMID 29867849, 2018). "Anthrax toxin receptor 1/tumor endothelial marker 8/(ANTXR1 or TEM8) is a transmembrane protein that is up-regulated in tumor-associated vasculature and can serve as a receptor for the binding moiety of anthrax toxin." (PMID 26785120, 2016). "Indeed, a recent study shows that solid tumor growth depends upon collagen binding and uptake mediated by the TEM8/ANTXR1 cell surface protein in tumor-associated stromal cells." (PMID 39056792, 2024). "ANTXR1 expression has been linked to different proteins that may be interacting with TEM8 in the membrane, but to understand its role of tumor prognosis we analyzed the expression level of different membrane proteins and how it was impacting OS and PFS." (PMID 39917181, 2024). "TEM8/ANTXR1 has been described as a marker for pathological, tumor-associated angiogenesis, which promotes tumor growth and may mediate resistance to therapies targeting angiogenesis." (PMID 36090051, 2022). "In addition, overexpression of TEM8/ANTXR1 in the setting of hypoxic tumor microenvironments is associated with the presence of cancer stem cells, increased stem cell self-renewal and increased metastasis in a Wnt pathway dependent mechanism." (PMID 36090051, 2022). "However, in previous studies high ANTXR1 expression has been correlated with tumor associated macrophage differentiation and immunosuppression factor in the TME suggesting that the immune score might be low." (PMID 39917181, 2024). "ANTXR1 or TEM8 is significantly overexpressed in various tumor cells and silencing TEM8 leads to reduced cell proliferation, invasion, and metastasis, along with an increase in apoptosis, underscoring its role in the development of cancer development." (PMID 41003524, 2025).